FGF23 (fibroblast growth factor 23)
Diseases named in the same sentence as FGF23 in open-access papers (continued):
Sharing a sentence is not in itself a finding about the gene and the disease.
hypoparathyroidism (15 papers, 2015 to 2025). Hypoparathyroidism is an endocrine disorder in which the parathyroid glands in the neck do not produce enough parathyroid hormone (PTH). "The aim of this study was to evaluate the association of ferritin, intact PTH, FGF23, and l,25(OH)2D3 in patients with major thalassemia having normal parathyroid function and hypoparathyroidism." (PMID 33198660, 2020). "Other animal studies with hypoparathyroidism or calcium deficiency also demonstrated that serum phosphate values are inversely correlated with serum FGF-23 values." (PMID 26186634, 2015). "This is linked to disturbances in bone-regulating factors, including relative hypoparathyroidism and changes in hormones, like FGF-23, sclerostin, and klotho, leading to bone disease." (PMID 39941397, 2025). "Hypoparathyroidism attenuates the TmP/GFR lowering effect of FGF23 excess, such that hypophosphatemic bone disease is ameliorated." (PMID 33615106, 2021). "A very recent and well-conducted clinical study has shed light on the interdependent physiology of PTH and FGF-23 in patients with hypoparathyroidism." (PMID 34884774, 2021). "In spite of many strengths of this study that evaluated FGF23 function in hypoparathyroid patients, we had some limitations." (PMID 32398014, 2020). "Future clinical trials should be conducted on patients with hypoparathyroidism after PTH treatment to investigate the FGF23 functions more accurately." (PMID 33198660, 2020). "Serum FGF-23 was higher in patients with hypoparathyroidism in comparison with the control group (P = 0.001)." (PMID 32398014, 2020). "Serum phosphorus and FGF23 levels were significantly higher in patients with hypoparathyroidism (5.9 ± 1.6 mg/dL, and 381.9 ± 175 pg/mL) than the control group (4.8 ± 0.8 mg/dL, and 241.2 ± 121.0 pg/mL) (P = 0.002 and P = 0.005 respectively)." (PMID 33198660, 2020). "The fractional excretion of phosphorous was lower in patients with hypoparathyroidism, despite the high level of FGF23 (P = 0.001)." (PMID 33198660, 2020). "We found high serum level of phosphate and FGF-23 in hypoparathyroid patients compared to the control group (P < 0.001 and P < 0.001, respectively)." (PMID 32398014, 2020). "Animal studies also showed that PTH-null mice experienced high PO4 in spite of high circulating FGF-23, resembling participants with hypoparathyroidism in the present study." (PMID 32398014, 2020). "Median plasma FGF-23 level in patients with hypoparathyroidism was significantly lower than that of normoparathyroid patients (34.8 vs 43.1 pg/mL, p=0.048) although serum P levels and serum PTH levels were comparable." (PMID 29726397, 2018). "In patients with hypoparathyroidism, median plasma FGF-23 level was significantly lower than that of normoparathyroid patients [34.8 (2.1-120.0) vs 43.1 (3.2-242.8) pg/mL, p=0.048]." (PMID 29726397, 2018). "Plasma FGF-23 level in patients with hypoparathyroidism was lower than that of patients with normoparathyroidism." (PMID 29726397, 2018). "In other words, it might be that higher FGF-23 levels are required to produce phosphate wasting in patients with hypoparathyroidism." (PMID 34884774, 2021). "FGF23 was higher in the patients with hypoparathyroidism than the controls (P = 0.002)." (PMID 33198660, 2020). "Hence, future clinical trials are suggested on patients with hypoparathyroidism before treatment to investigate the FGF23 functions and its interaction with PTH more accurately, considering tissue iron evaluation e.g. in liver." (PMID 33198660, 2020). "In addition, we have done an analysis in our hypoparathyroid patients evaluating the association of FGF23 and serum calcium in 2 separate group of low calcium and normal calcium level." (PMID 32398014, 2020). "One would expect to see elevated serum P levels in these hypoparathyroid patients because of impairment of both phosphaturic hormones, PTH and FGF-23." (PMID 29726397, 2018).
hypoparathyroidism (continued). "Cinacalcet is hypothesized to mitigate the effects of paraneoplastic FGF23 in TIO by activating parathyroid gland calcium-sensing receptors, inducing hypoparathyroidism, resulting in increased renal retention of phosphate." (PMID 39734682, 2024). "Further studies are also suggested to evaluate the role of ferritin on PTH, FGF23 in normal population with and without hypoparathyroidism and also in other genotypes of thalassemia." (PMID 33198660, 2020). "Subjects with hypoparathyroidism, typically with very low or undetectable PTH levels, have high serum phosphorus and FGF23, consistently with PTH requirements for a full phosphaturic FGF23 effect." (PMID 30736285, 2019). "Plasma intact FGF-23 level in hypoparathyroid patients was lower than that of normoparathyroid patients." (PMID 29726397, 2018). "However, serum ferritin level in patients with hypoparathyroidism did not correlate with the levels of serum FGF23, calcium, phosphorous, PTH, 25(OH) D, 1,25(OH)2D3, and FEPh (P > 0.05)." (PMID 33198660, 2020). "Thus, in this PTX+CKD group with hypoparathyroidism and low FGF-23 levels, phosphaturia had not increased, although the CKD group had increased fractional excretion of phosphate (as expected in CKD)." (PMID 26186634, 2015). "Hence, we conducted this case – control study to evaluate whether the renal excretion of PO4 by serum FGF-23 in patients with hypoparathyroidism was different from normal population or not." (PMID 32398014, 2020). "Hence, the present study on hypoparathyroid patients and normal population provides an opportunity to observe whether the phosphaturic effect of FGF-23 is independent of PTH or not." (PMID 32398014, 2020). "Also, we found a strong positive correlation between serum FGF-23 and FE PO4 in the control population, but this correlation was absent in hypoparathyroid patients." (PMID 32398014, 2020).
nephrocalcinosis (15 papers, 2014 to 2025). Nephrocalcinosis is a disorder that occurs when too much calcium is deposited in the kidneys. "Phosphorus therapy is associated with diarrhoea and is a stimulant to PTH secretion as well as FGF23 secretion; it is associated with nephrocalcinosis in treated patients with XLH and thus normalisation of serum phosphorus is not the target of therapy in XLH." (PMID 24594262, 2014). "In brief, the simultaneous presence of HP loading and high FGF23 levels may be a risk factor for nephrocalcinosis in patients with XLH." (PMID 32184468, 2020). "The mechanism by which FGF23/FGFR1 signaling aggravates nephrocalcinosis induced by HP intake remains to be clarified." (PMID 32184468, 2020). "Similar findings were observed in osteopontin levels, which support the suggestion of Experiment 1 that FGF23 and osteopontin are involved in HP-induced nephrocalcinosis." (PMID 32184468, 2020). "Our findings suggest that FGF23 is involved in nephrocalcinosis induced by HP intake partially through FGFR1 signaling." (PMID 32184468, 2020). "A recent study has also shown that upregulation of OPN via FGF23/PHEX can contribute to nephrocalcinosis and nephrolithiasis observed in mice on a high-phosphate diet." (PMID 30808384, 2019). "The current treatment for FGF23-dependant HR is oral phosphate replacement and calcitriol which have potential treatment complications such as calciuria and nephrocalcinosis." (PMID 29280738, 2017). "Furthermore, FGF23 was involved in the nephrocalcinosis induced by high phosphorus intake partially through FGFR1 signaling." (PMID 32184468, 2020). "Therefore, estrogenic action on the bone aggravates nephrocalcinosis induced by HP intake, possibly through stimulating FGF23 in the bone." (PMID 32184468, 2020). "Treatment should not attempt to normalize serum phosphate levels by giving aggressive phosphate therapy as this might lead to side effects such as diarrhea, secondary hyperparathyroidism, increased FGF23 synthesis, nephrocalcinosis and renal insufficiency." (PMID 29280738, 2017). "Subsequently, we hypothesized that estrogenic action on the bone may influence nephrocalcinosis induced by HP intake by stimulating FGF23, because an in vitro study has reported that estrogen increased mRNA expression and protein levels of FGF23 in osteoblast-like cells." (PMID 32184468, 2020). "Serum FGF23 might also serve as a biomarker of phosphate-induced nephrocalcinosis." (PMID 32184468, 2020). "Additional studies, including plasma FGF23, PTH, iCa, and urinary calcium and phosphate measurements, are warranted to characterize whether these factors play a more important role in nephrocalcinosis." (PMID 35043997, 2022). "In fact, nephrocalcinosis has not been reported in anti-FGF23 antibody therapy in patients with XLH29, which supports our findings." (PMID 32184468, 2020). "Nephrocalcinosis has not been observed during FGF23-blocking trials, probably because the treatment does not include active vitamin D; however, long-term data are lacking." (PMID 30808384, 2019). "Unfortunately, data on FGF23, PTH, and urinary electrolytes were not available in our study; and hence, their involvement in nephrocalcinosis could not be investigated." (PMID 35043997, 2022).
metabolic bone disorder (14 papers, 2016 to 2026). A group of disorders that affect the bones secondary to increased levels of minerals or deficient levels of minerals such as calcium, magnesium, phosphorus, and vitamin D. Representative examples are osteomalacia, osteoporosis, and Paget disease. "Moreover, the absence of a control group and longitudinal follow-up data limits our ability to establish causal relationships or determine FGF23’s predictive value for metabolic bone disorders." (PMID 38951759, 2024). "In general, CKD is associated with mineral and bone metabolism disorders arising due to either one or a combination of the following factors: abnormalities of phosphorus, Fibroblast Growth Factor-23 (FGF23), calcium, parathyroid hormone (PTH), and vitamin D metabolism." (PMID 32257685, 2020). "Briefly, FGF23-Klotho signaling axis is a pivotal regulator of mineral and bone metabolic disorder in CKD–MBD." (PMID 33708111, 2020). "FGF23-Klotho signaling axis is reported to be useful for regulating mineral and bone metabolic disorder in CKD–MBD." (PMID 33708111, 2020). "All we can conclude is that children having relapsing INS treated with steroids have higher levels of Scl and FGF-23 that can indicate the bone metabolism disorder." (PMID 31354894, 2019). "Children having relapsing INS treated with steroids have higher levels of Scl and FGF-23 that can indicate the bone metabolism disorders." (PMID 31354894, 2019). "Tumor-induced osteomalacia (TIO) is a rare acquired metabolic bone disorder occurring as a result of isolated renal phosphate wasting due to abnormal tumor production of fibroblast growth factor 23 (FGF23)." (PMID 27709474, 2016). "Consequently, targeting FGF23-Klotho signaling axis in response to renal injury and its correlative mineral and bone metabolic disorder has been identified as multi-targets in the treatment of CKD–MBD." (PMID 33708111, 2020). "FGF-23 has been established as a reliable marker of bone metabolism disorders due to CKD." (PMID 31354894, 2019). "ROD is a metabolic bone disorder characterized by abnormal bone remodeling, accompanied by a pattern of changes in serum calcium, phosphate, parathyroid hormone (PTH), vitamin D, and fibroblast growth factor 23 (FGF-23)." (PMID 37870853, 2023).
fibrosis (13 papers, 2016 to 2025). the formation of excess fibrous connective tissue in an organ or tissue in a reparative or reactive process. "In 5/6 nephrectomised rats as experimental model of uraemia, an increase in size of myocyte as well as enhanced cardiac fibrosis together with induction of cardiac Fgf23 and RAAS-associated gene expression was overserved." (PMID 34422725, 2021). "We studied the associations of calcium, phosphate, 25D, PTH, FGF23, Klotho and T50 with histological fibrosis." (PMID 28036331, 2016). "Further investigation highlighted the pivotal role of VCAN_eCAF in remodeling the tumor fibrosis in the tumor microenvironment of Fibrosis+ LM, emphasizing potential targetable interactions such as FGF23 or FGF3-FGFR1." (PMID 41258075, 2025). "Animal models have identified FGF23 as a paracrine factor secreted by cardiomyocytes to promote cardiac fibrosis under conditions where TGF-β is activated." (PMID 36831276, 2023). "Overexpression of fibroblast growth factor 23 (FGF23) augmented cardiac fibrosis and hypertrophy in Ang II administered mice via PPARα/PLCγ-NFAT1/TGF-β signaling." (PMID 34489714, 2021). "Taken together, our data suggest that a chronic high phosphate load directly, and not via increased FGF23 concentration, causes proximal tubular damage with tubulointerstitial fibrosis and the concomitant formation of perivascular TLS." (PMID 41384828, 2025). "Through in vivo and in vitro experiments, we suggest that FGF-23 could not only lead to renal tubular fibrosis directly but could also activate the fibrotic TGFβ/Smad and Wnt/β-catenin pathways." (PMID 37016338, 2023). "Moreover, in vitro studies in post-MI-rodents, reported that increased cardiac FGF23 expression drives cardiac fibrosis via activation of β-catenin which is a well-known pro-fibrotic factor that interacts with TGF- β signaling." (PMID 36831276, 2023). "FGF-23 in activated macrophages infiltrating hypertrophic hearts may contribute to cardiac fibrosis and abnormal expression of FGF-23 in cardiomyocytes." (PMID 30120363, 2018). "CRS mice showed a significant increase of circulatory and renal FGF23 protein levels, as well as an upregulation of p-GSK, active-β-catenin, TGF-β, collagen I and vimentin, a downregulation of renal Klotho expression and induction of cardiorenal dysfunction and cardiorenal fibrosis." (PMID 33460402, 2021).
kidney stone (13 papers, 2014 to 2026). "The aim of this study was to assess if sclerostin or FGF23 are associated with derangements of mineral metabolism or other metabolic or demographic factors in our cohort of recurrent kidney stone formers (rKFs)." (PMID 38186870, 2024). "In conclusion, our data reveal a robust association of RAS activity with circulating FGF23 in kidney stone formers." (PMID 35201364, 2022). "Our data reveal a robust association of RAS activity with circulating FGF23 levels in kidney stone formers." (PMID 35201364, 2022). "In the present study, we found that the major urinary metabolite of aldosterone, tetrahydroaldosterone, quantified in 24 h urines by a sensitive and specific GC–MS assay is positively associated with FGF23 concentrations in plasma of kidney stone formers." (PMID 35201364, 2022). "Of itself, urinary phosphate is not a significant lithogenic factor, but recent studies linking phosphate intake, serum FGF23 levels, kidney stone formation, and cardiovascular risk deserve more attention." (PMID 27981376, 2017). "Indeed, dysregulated Pi may be a potential common risk factor mediating associations between elevated levels of FGF23, kidney stones, and renal cell carcinoma, and more research is needed in these areas." (PMID 40643473, 2025). "Additionally, the authors of an analysis of participants in the Health Professionals Follow-Up Study suggested that higher FGF23 levels may be associated with risk for kidney stones, even though the association was on the borderline of statistical significance." (PMID 40643473, 2025). "In our prospective controlled study, we investigated sclerostin and FGF23 in rKSFs and controls to test their potential role in recurrent kidney stone formers." (PMID 38186870, 2024). "Based on a well-characterized single-center registry of patients with kidney stones, we report that RAS activity surveyed by the urinary excretion rate of metabolite tetrahydroaldosterone is independently associated with circulating FGF23." (PMID 35201364, 2022). "However, after adjusting for multiple covariates, the odds ratios of incident symptomatic kidney stones in the highest compared with lowest quartiles were 1.73 (P for trend 0.01) for 1,25(OH)2D and 1.45 (P for trend 0.03) for FGF23." (PMID 26332888, 2015). "Whether changes in FGF23 are involved in kidney stone formation is unexplored." (PMID 25166750, 2014). "Taken together, earlier studies and the results of this investigation do not suggest a major contribution of FGF23 to kidney stone pathophysiology in patients with or without renal phosphate leak even though the issue deserves future scrutiny." (PMID 38186870, 2024). "We found a non-significant trend to higher plasma FGF23 concentrations in women, but our dataset consisted largely of men—representing the sex difference in incidence of kidney stones." (PMID 35201364, 2022). "The role of FGF23 in kidney stones formation has not been clarified yet." (PMID 38186870, 2024). "Thus, the role of FGF23 in nephrolithiasis is still not well defined." (PMID 38186870, 2024). "While direct associations of FGF23 SNP2 or SNP3 with phosphate metabolism have not previously been described, minor allele homozygosity of SNP1 is related to lower phosphate concentrations in adult nephrolithiasis patients and a smaller cohort of school-aged children." (PMID 37284066, 2023).
primary hyperparathyroidism (13 papers, 2010 to 2025). "In endocrine pathologies such as primary hyperparathyroidism (PHPT), EPO resistance is mediated by elevated fibroblast growth factor 23 (FGF23), a hormone implicated in phosphate homeostasis, inflammation, and erythropoiesis." (PMID 41012526, 2025). "Recent evidence shows elevated FGF23 in primary hyperparathyroidism." (PMID 33815294, 2021). "Conversely, PTH may stimulate FGF-23 secretion by osteoblasts, because the FGF-23 levels of rodents with primary hyperparathyroidism (HPT) are increased, which may be reduced by parathyroidectomy." (PMID 21234310, 2010). "As parathyroid hormone (PTH) can be elevated because of FGF23 excess in patients with TIO, primary hyperparathyroidism is also a common misdiagnosis." (PMID 36511653, 2023). "Because these findings were not attributed to the serum level of phosphorus, serum calcium was suggested to be another determinant for FGF23 based upon its correlation with FGF23 independent of phosphorus in primary hyperparathyroidism." (PMID 35903313, 2022). "This is in contrast to the results of another study, which examined changes in FGF23 levels after PTX for primary hyperparathyroidism and demonstrated no change between day 1 and 6 weeks after PTX." (PMID 27999806, 2016).